PDLIM5 (PDZ and LIM domain 5)
Description:
May play an important role in the heart development by scaffolding PKC to the Z-disk region. May play a role in the regulation of cardiomyocyte expansion. Isoforms lacking the LIM domains may negatively modulate the scaffolding activity of isoform 1. Overexpression promotes the development of heart hypertrophy. Contributes to the regulation of dendritic spine morphogenesis in neurons. May be required to restrain postsynaptic growth of excitatory synapses. Isoform 1, but not isoform 2, expression favors spine thinning and elongation.
Synonyms: ENH; L9; LIM; ENH1
Tractability: Antibody: the Human Protein Atlas places it where antibodies can reach. PROTAC: UniProt records ubiquitination sites on it; ubiquitination databases record sites on it; its protein half-life has been measured.
Gene: Protein-coding gene on chromosome 4 (94,451,857 to 94,668,227, forward strand). Ensembl gene ENSG00000163110.
Subcellular location: Postsynaptic density; Presynapse; Postsynapse; Cytoplasm, cytosol
Subcellular location (Human Protein Atlas): Plasma membrane; Focal adhesion sites; Nucleoplasm
Pathways (Reactome):
Neuronal System: Neurexins and neuroligins
Gene Ontology:
Molecular function: cadherin binding involved in cell-cell adhesion; protein binding; actin binding; actinin binding; muscle alpha-actinin binding; protein kinase C binding
Biological process: actin cytoskeleton organization; cell growth involved in cardiac muscle cell development; heart development; muscle structure development; regulation of dendritic spine morphogenesis; regulation of synapse assembly; cell-cell adhesion
Cellular component: actin cytoskeleton; adherens junction; cytosol; filamentous actin; membrane; postsynapse; postsynaptic density; presynapse; stress fiber; Z disc
Genetic constraint (gnomAD): Loss-of-function variants: 11 observed, 20.07 expected, observed/expected ratio (o/e) 0.55, 90% interval 0.34 to 0.91. The upper end of that interval is the gene's LOEUF score, 0.91, which puts it in group 3 of 6, group 1 being the genes least tolerant of losing a copy. Missense variants: 320 observed, 348.19 expected, observed/expected ratio (o/e) 0.92, 90% interval 0.84 to 1.01. Synonymous variants: 117 observed, 130.92 expected, observed/expected ratio (o/e) 0.89, 90% interval 0.77 to 1.04.
Homologues: Orthologues: macaque PDLIM5 (97% identical), dog PDLIM5 (91% identical), rat Pdlim5 (88% identical), chimpanzee PDLIM5 (80% identical), rabbit PDLIM5 (75% identical), guinea pig PDLIM5 (74% identical), mouse Pdlim5 (73% identical), pig PDLIM5 (72% identical), tropical clawed frog pdlim5 (68% identical), zebrafish pdlim5b (55% identical), zebrafish pdlim5a (52% identical), Caenorhabditis elegans alp-1 (30% identical), and 1 more. Paralogues in human: LDB3 (42% identical), PDLIM7 (38% identical), PDLIM1 (17% identical), PDLIM4 (15% identical), PDLIM3 (15% identical), PRICKLE4 (13% identical), PDLIM2 (12% identical).
Diseases named in the same sentence as PDLIM5 in open-access papers:
PDLIM5 is named in the same sentence as 54 diseases in open-access papers, as found by Europe PMC text mining. Sharing a sentence is not in itself a finding about the gene and the disease. The quoted sentences say what the papers report.
cardiac hypertrophy (13 papers, 2017 to 2025). "Among them, Csrp3, Pdlim5, Sorbs2, Rcan1, and Acta1, which were related to cardiac hypertrophy and remodeling, were upregulated and modified by at least one active histone mark." (PMID 33330655, 2020). "miR-21-3p-enriched exosomes are also released by cardiac fibroblasts in the mouse model of cardiac hypertrophy, and exosomal miR-21-3p silences SORBS2 and PDLIM5 in cardiomyocytes resulting in cardiac hypertrophy." (PMID 32596327, 2020). "Additionally, Gde1, which is involved in skeletal muscle development, Pdlim5, a promoter of cardiac hypertrophy, and Ppp1cb, a regulator of cell division, glycogen metabolism, and muscle contractility, were overexpressed." (PMID 31480808, 2019). "Specifically, when miR-21* is transported into cardiomyocytes, it targets SORBS2 (sarcoplasmic protein adsorption and SH3 domain-containing protein 2) and PDLIM5 (PDZ and LIM domain 5), promoting cardiac hypertrophy in the mouse pressure overload model." (PMID 41515974, 2025). "Specifically, previous studies identified that exosomal miR-21-3p is transported into cardiomyocytes, where it targets SORBS2 and PDLIM5 (PDZ and LIM domain 5), contributing to cardiac hypertrophy." (PMID 39850481, 2024). "Exosome-derived miR-21-3p reportedly triggers cardiac hypertrophy via sorbin and SH3 domain-containing protein 2 (SORBS2) and PDZ and LIM domain 5 (PDLIM5)." (PMID 38355681, 2024). "Transfer of miR-21* from cardiac fibroblasts to CMs induced cardiac hypertrophy by downregulating Sorbin and SH3-domain-containing protein 2 and PDZ and LIM domain 5 (PDLIM5)." (PMID 29209616, 2017). "Additionally, exosome-derived miR-21-3p has been identified as a key mediator in cardiac hypertrophy through its regulatory impact on sorbin and SH3 domain containing 2 (SORBS2) and PDZ and LIM domain 5 (PDLIM5)." (PMID 38398032, 2024).
prostate carcinoma (9 papers, 2013 to 2025). A carcinoma that arises from epithelial cells of the prostate gland. "The potential of PDLIM5 as an oncogene has been implicated in the progression of prostate cancer where its silencing leads to restrained prostate cancer colony formation and induced apoptosis, as well as confirmed inhibition of tumor growth in nude mice." (PMID 33101368, 2020). "Collectively, lncRNA AGAP2-AS1 silencing inhibited the expression of PDLIM5, and weakened the proliferation, migration and invasion of prostate cancer cells via miR-195-5p up-regulation in vitro." (PMID 33101368, 2020). "Taken together, the key findings of our study demonstrated that lncRNA AGAP2-AS1 silencing exerted suppressive effects on the development of prostate cancer via the miR-195-5p-dependent downregulation of PDLIM5." (PMID 33101368, 2020). "The current study aimed to elucidate the role of lncRNA AGAP2-AS1/miR-195-5p/PDZ and LIM domain 5 (PDLIM5) in prostate cancer progression." (PMID 33101368, 2020). "Here, we found that PDLIM5 was abnormally upregulated in prostate cancer (PCa) tissues as compared with that in normal prostate tissue." (PMID 29228678, 2017). "In summary, miR-195-5p could target PDLIM5 and suppress the proliferation, migration and invasion abilities of prostate cancer cells in vitro." (PMID 33101368, 2020). "In conclusion, the key findings of our study presented evidence suggesting that the down-regulation of lncRNA AGAP2-AS1 inhibited PDLIM5 expression, which ultimately impedes prostate cancer development and progression through up-regulating miR-195-5p expression." (PMID 33101368, 2020). "Hence, the central objective of the current study was to investigate the relationships among lncRNA AGAP2-AS1, miR-195-5p, and PDLIM5, and their regulatory mechanism influencing cell proliferation, migration and invasion of prostate cancer cells." (PMID 33101368, 2020). "Furthermore, PDLIM5 has been reported to be abnormally enriched in prostate cancer tissues, with its knockdown shown to trigger suppression of proliferative, migratory and invasive abilities of prostate cancer cells." (PMID 33101368, 2020). "Similarly, our study also suggested that miR-195-5p inhibited prostate cancer progression by inhibiting its target PDLIM5." (PMID 33101368, 2020). "During the present study, our results demonstrated that lncRNA AGAP2-AS1 silencing could inhibit PDLIM5 expression, and impede prostate cancer development and progression through the up-regulation of miR-195-5p expression." (PMID 33101368, 2020). "Besides, lncRNA AGAP2-AS1 could bind to miR-195-5p which targeted PDLIM5 and subsequently downregulated its expression, ultimately impeding the progression of prostate cancer." (PMID 33101368, 2020). "Furthermore, the SNP lies in the intronic region of the PDLIM5 gene and could contribute to alternative splicing patterns observed in prostate cancer cells as compared to normal cells instead of providing allele dosage effects on prostate cancer risk." (PMID 28784146, 2017). "Among men carrying the variant allele at the PDLIM5 SNPs rs1859962 or rs17021918 increased prostate cancer risk was observed with high compared to no terbufos use (OR = 2.05, 95% CI: 1.16–3.64, P-interaction = 0.037), (OR = 1.59, 95% CI: 1.03–2.45, P-interaction = 0.042), respectively." (PMID 23593118, 2013).
schizophrenia (7 papers, 2007 to 2024). A major psychotic disorder characterized by abnormalities in the perception or expression of reality. "Pdlim5 deficiency in heterozygotes had a protective effect on schizophrenia-like phenotypes in chronic and acute methamphetamine-induced locomotor hyperactivity in the open field (METH-ILAT) and methamphetamine impairment of PPI." (PMID 25762938, 2015). "PDZ and LIM domain 5 (PDLIM5) has been associated with schizophrenia, depression, and bipolar disorder in human genetic and expression studies." (PMID 25762938, 2015). "Recent studies have shown that SNPs in the PDLIM5 gene are associated with schizophrenia, bipolar disorder, and major depression." (PMID 23593136, 2013). "PDLIM5 polymorphisms have been associated with schizophrenia (rs2433320 and rs2433322) and bipolar disorder (rs10008257 and rs2433320)." (PMID 17903297, 2007). "Nevertheless, the data suggest that increased Plim5 levels may cause schizophrenia-like behavioral phenotypes, whereas decreased Pdlim5 may result in depression." (PMID 25762938, 2015). "Despite these limitations, the present study indicates that the increased expression of PDLIM5 may cause behavioral changes to patients with mania or schizophrenia-like symptoms, whereas a decrease in its expression may cause depression." (PMID 23593136, 2013). "We used Pdlim5 hetero KO mice, because an increase or reduction of PDLIM5 expression in human brains, peripheral lymphoblastoid cells, and lymphocytes has been reported to be linked with schizophrenia and mood disorders." (PMID 23593136, 2013). "It should be noted that there is a difference in the expression level of the PDLIM5 gene in the peripheral blood cells of patients with major depressive disorder and schizophrenia who were undergoing treatment with antidepressants and antipsychotics." (PMID 23593136, 2013). "The PDLIM5 mRNA expression levels in the peripheral leukocytes of medication-free patients with schizophrenia were significantly higher than in those of control subjects." (PMID 23593136, 2013). "Iwamoto and colleagues used DNA chip analysis to examine the prefrontal regions of postmortem brains of patients with mental disorders, and found that PDLIM5 was upregulated in patients with schizophrenia, bipolar disorder and major depression." (PMID 23593136, 2013). "In genetic association studies, single nucleotide polymorphisms (SNPs) that are located in the upstream region of PDLIM5 have been found to be associated with BPD, schizophrenia, and major depressive disorder." (PMID 23031404, 2012). "In contrast, other studies have reported no significant genetic association between the PDLIM5 gene and schizophrenia." (PMID 23593136, 2013). "These contrasting findings in the association between antipsychotics and PDLIM5 expression may relate to differences in the disease condition, that is, BPD and schizophrenia, or to antipsychotic medication other than olanzapine." (PMID 23031404, 2012). "Hence, Pdlim5 may affect schizophrenia and depression-related behaviors through regulation of Ca2+ channels as well as synapse regulation." (PMID 25762938, 2015). "The same group of authors reported an increased expression of PDLIM5 in peripheral leukocytes in medication-free patients with schizophrenia but not in patients administered antipsychotic medication." (PMID 23593136, 2013). "Our results support previous findings that showed a significant decrease in PDLIM5 mRNA expression in the lymphoblastoid cell lines of BPD and schizophrenia patients, as well as in the PBLs of patients with major depressive disorder, compared with that in control subjects." (PMID 23031404, 2012).
depression (6 papers, 2012 to 2024). "Pdlim5-deficient heterozygotes expressed a depression-like phenotype in the TST that was rescued by the antidepressant imipramine." (PMID 25762938, 2015). "The PDLIM5 (PDZ and LIM domain 5) gene has been genetically associated with mood disorders; it’s expression is upregulated in the postmortem brains of patients with bipolar disorder and downregulated in the peripheral lymphocytes of patients with major depression." (PMID 23593136, 2013). "Iga and colleagues also reported that decreased PDLIM5 levels returned to normal after 8 weeks of medication in the peripheral lymphocytes of patients with depression." (PMID 23593136, 2013). "We conducted a forced swimming test, which is a common behavioral test for assessing depression in rodents and for testing the efficiency of antidepressant drugs, in Pdlim5 hetero KO mice." (PMID 23593136, 2013). "Additionally, PDLIM5 can play a role in the development of various diseases, including cancer, pulmonary hypertension, depressive disorders, and type 2 diabetes and hypertension, highlighting the significance of exploring the function of PDLIM5." (PMID 38667334, 2024). "In addition, significantly lower PDLIM5 mRNA expression levels have been reported in the peripheral leukocytes of drug-naïve patients with depression than in those of control subjects." (PMID 23593136, 2013).
dilated cardiomyopathy (6 papers, 2015 to 2024). Cardiomyopathy which is characterized by dilation and contractile dysfunction of the left and right ventricles. "A study reported that polymorphisms in PDLIM5 are associated with an increased risk of dilated cardiomyopathy." (PMID 38667334, 2024). "Among them, we found PDZ and LIM domain protein 5 (Pdlim5), a gene encoding for a protein that localizes to the Z-disk by binding to α-actinin, and which has been implicated in dilated cardiomyopathy and in heart failure with preserved ejection fraction." (PMID 35937994, 2022). "A PDLIM3 or PDLIM5 deficiency in mice leads to dilated cardiomyopathy." (PMID 31424159, 2019). "Loss of PDLIM5 has also been associated with dilated cardiomyopathy." (PMID 29216221, 2017). "LDB3 and PDLIM5 have both been implicated in dilated cardiomyopathy DCM." (PMID 26061177, 2015).
bipolar disorder (5 papers, 2007 to 2024). A disorder of the brain that causes unusual shifts in mood, energy, activity levels and the ability to carry out day-to-day tasks. "One of the genes suggested to play an important role in the pathophysiology of bipolar disorder (BPD) is PDLIM5, which encodes LIM domain protein." (PMID 23031404, 2012).
atherosclerosis (4 papers, 2019 to 2023). A disease characterized by the build-up of fatty material and calcium deposition in the arterial wall resulting in partial or complete occlusion of the arterial lumen. "This work suggests that Pdlim5 has the potential to be a drug target to suppress the development of atherosclerosis." (PMID 34368251, 2021). "Given that PDLIM5 is a pro-atherosclerotic gene, SARS-CoV-2 infection that results in increased PDLIM5 expression levels may accelerate atherosclerosis." (PMID 37109540, 2023). "One recent study reported that the inhibition of vascular smooth muscle cell migration through the Pdlim5 pathway by metformin, another AMPK activator, inhibited the progression of atherosclerosis, which is accelerated in diabetes." (PMID 37189631, 2023).
diabetes (4 papers, 2021 to 2025). "Associated cardiovascular diseases include diabetes (PDLIM5, HDAC4, and TLE1), cardiac development (PDLIM5) and myocardial aging (CASP12), hypertension (PFKP and TAB2), and intracerebral and intraventricular bleeding (RUNX1) and stroke (AXIN2)." (PMID 36620623, 2022). "A diabetes-specific targeted analysis showed negatively enriched Z-disc and contractile gene sets enriched due to the downregulation of CASQ2, peripherin (PRPH), nebulette (NEBL), titin-cap (TCAP), and LIM domain-binding proteins LDB3, PDLIM4, and PDLIM5 (Dataset EV36)." (PMID 40759793, 2025).
gastric cancer (4 papers, 2020 to 2021). A primary or metastatic malignant neoplasm involving the stomach. "As one among them, PDLIM5 is linked to a number of medical problems, including mental illnesses and heart diseases, and its expression has caused concern with the progression of gastric cancer, lung cancer, and breast cancer." (PMID 33916517, 2021). "A previous study revealed that siRNA-mediated PDLIM5 silencing inhibited gastric cancer cell proliferation and colony formation, and enhanced cell apoptosis." (PMID 33101368, 2020). "A previous study has found that PDLIM5 was highly expressed in gastric cancer cell lines and had critical role in cells growth." (PMID 32566649, 2020). "In view of the important role of PDLIM5 in cancer, some studies have indicated that it is involved in the growth of gastric cancer cells, and suggested that PDLIM5 silencing through the use of small interfering RNAs (si-RNA) may be a potential strategy for the treatment of gastric cancer." (PMID 32848888, 2020).
Hypertension (4 papers, 2020 to 2024). The presence of chronic increased pressure in the systemic arterial system. "Moreover, the methylation of cg20305610 and cg24450312 was also associated with increased risk of incident NAFLD, and their related PDLIM5 and RASSF5 genes have been reported to correlate with obesity, type 2 diabetes, and hypertension previously." (PMID 37605101, 2024).
alcohol dependence (3 papers, 2017 to 2020). Physical and psychological dependence on alcohol. "While many identified genes were generally in alignment with prior knowledge, further work should be done to understand the associations between alcoholism and the five genes that went uncorroborated in the literature (BLNK, BMPER, PDLIM5, VEPH1, AMPD3)." (PMID 28361705, 2017).
breast carcinoma (3 papers, 2015 to 2023). "To assess the role of PDLIM5 in breast cancer progression, we performed in vivo lung colonization assays with control and PDLIM5-deficient MDA-MB-231 and HCC1806 cells." (PMID 37156909, 2023). "In our model, PDLIM5 depletion impacts breast cancer progression due to HNRNPC deficiency." (PMID 37156909, 2023). "Furthermore, in agreement with PDLIM5 being a functional effector downstream of the HNRNPC–PABPC4 axis, PDLIM5 expression was also associated with survival of patients with breast cancer." (PMID 37156909, 2023). "Indeed, an ectopic PDLIM5 expression in HNRNPC-deficient cells was sufficient to reduce the lung metastatic burden to the levels similar to control cells with intact HNRNPC expression, in line with HNRNPC acting upstream of PDLIM5 to control breast cancer metastasis." (PMID 37156909, 2023).
idiopathic dilated cardiomyopathy (3 papers, 2019 to 2022). Decreased function of the heart associated with cardiac enlargement and congestive heart failure, of unknown cause. "Recently, SNPs in PDLIM3 and PDLIM5 have been implicated in the development of idiopathic dilated cardiomyopathy." (PMID 36531944, 2022).
Alzheimer disease (2 papers, 2007 to 2025). A progressive, neurodegenerative disease characterized by loss of function and death of nerve cells in several areas of the brain leading to loss of cognitive function such as memory and language. "Additionally the PDLIM5 protein is a homolog of AD7c-NTP, a neural thread protein associated with Alzheimer's disease, and is being studied as a possible CSF biomarker of AD." (PMID 17903297, 2007).
cardiomyopathy (2 papers, 2019 to 2022). A disease of the heart muscle or myocardium proper. "PDLIM5 plays a differential role in various organs and is associated with vascular remodeling and cardiomyopathy." (PMID 36620623, 2022).
heart failure (2 papers, 2022 to 2024). Inability of the heart to pump blood at an adequate rate to meet tissue metabolic requirements. "During heart failure, HNRNPC physically interacts with myocardial ganglion proteins FHL2, PDLIM5, and MYH7 in the heart." (PMID 38916731, 2024).